UMAD1 (UBAP1-MVB12-associated (UMA) domain containing 1)
Synonyms: RPA3-AS1; RPA3OS
Tractability: PROTAC: ubiquitination databases record sites on it; its protein half-life has been measured.
Gene: Protein-coding gene on chromosome 7 (7,640,661 to 7,968,020, forward strand). Ensembl gene ENSG00000219545.
Subcellular location (Human Protein Atlas): Nucleoplasm
Gene Ontology:
Molecular function: protein binding
Homologues: Orthologues: chimpanzee UMAD1 (99% identical), macaque UMAD1 (87% identical), pig UMAD1 (86% identical), rabbit UMAD1 (82% identical), guinea pig UMAD1 (77% identical), mouse Umad1 (75% identical), rat Glcci1 (75% identical), tropical clawed frog umad1 (41% identical), zebrafish umad1 (38% identical).
Diseases named in the same sentence as UMAD1 in open-access papers:
UMAD1 is named in the same sentence as 3 diseases in open-access papers, as found by Europe PMC text mining. Sharing a sentence is not in itself a finding about the gene and the disease.
UMAD1 shares sentences with these, for which no sentence is quoted: Ataxia (1 paper); interstitial lung disease (1); rheumatoid arthritis (1).